FGF23 (fibroblast growth factor 23)
Diseases named in the same sentence as FGF23 in open-access papers (continued):
Sharing a sentence is not in itself a finding about the gene and the disease.
hypophosphatemia (423 papers, 2008 to 2026). Lower than normal levels of phosphates in the circulating blood. "Studies indicate that TIO, which affects both men and women equally and typically manifests between the ages of 40 and 45, is the most prevalent acquired cause of FGF23-mediated hypophosphatemia." (PMID 41438661, 2026). "Burosumab is a human monoclonal antibody against FGF23 that reduces the risk of developing FGF23-mediated hypophosphatemia and its associated complications." (PMID 40297189, 2025). "In particular, the clinical and biomedical characteristics of XLH are largely delineated in bone tissue, as high FGF23 levels lead to renal phosphate loss, hypophosphatemia, skeletal deformities, and mineralization defects." (PMID 40926139, 2025). "An excess secretion of FGF-23 causes hypophosphatemia and is classically described as tumor-induced osteomalacia (TIO), a condition with FGF-23-producing tumors." (PMID 41583152, 2025). "One known side effect of intravenous iron treatment is hypophosphatemia, particularly with ferric carboxymaltose, which has been associated with increased fibroblast growth factor 23 (FGF23) production that suppresses renal phosphate reabsorption." (PMID 41035806, 2025). "This strongly suggests that the expression of the Fgfr1+/N330I variant in bone drives FGF23 excess leading to hypophosphatemia, which in turn leads to systemic undermineralization of bone." (PMID 41473314, 2025). "We used CRISPR/Cas9 technology to generate a knock-in mouse model expressing the disease-causing FGFR1 variant, p.N330I, chosen because of its frequency and its association with FGF23 excess and hypophosphatemia in patients." (PMID 41473314, 2025). "The members of the advisory board agreed that clinical chemistry and laboratory tests can certainly, in the early stages of the diagnostic process, lead towards the exclusion of FGF23-independent forms of hypophosphatemia." (PMID 39377903, 2025). "Tumor-induced osteomalacia (TIO) is a paraneoplastic syndrome caused by fibroblast growth factor 23 (FGF23)-producing tumors originating from soft tissue and bone; it is characterized by hypophosphatemia and fragility fractures." (PMID 39866919, 2025). "A key diagnostic hallmark is hypophosphatemia accompanied by low or inappropriately normal 1,25-dihydroxyvitamin D (1,25 Vit D) levels, reflecting FGF-23's inhibition of renal 1-alpha-hydroxylase (CYP27B1) despite the stimulatory effects of low phosphate." (PMID 40951211, 2025). "FDI, in contrast, has been reported to cause less elevation in FGF23, resulting in a lower risk of hypophosphatemia." (PMID 41035806, 2025). "Central to diagnosis is recognizing hypophosphatemia with low or inappropriately normal 1,25 Vit D as a hallmark of TIO, reflecting FGF-23's suppression of CYP27B1 despite hypophosphatemia's stimulatory effect." (PMID 40951211, 2025). "Tumor-induced osteomalacia (TIO) is a rare paraneoplastic syndrome due to a phosphaturic tumor, which overproduces FGF23, causing hyperphosphaturia, hypophosphatemia, low 1,25(OH)2D, and osteomalacia." (PMID 40329993, 2025). "Frank hypophosphatemia in patients with FD is infrequent and is caused by overproduction of fibroblast growth factor 23 (FGF23) by abnormal osteogenic precursors in FD lesions." (PMID 40297189, 2025). "Some studies reported that FGF23-mediated hypophosphatemia was associated with a higher prevalence of FD-related complications, including fractures, scoliosis, and skull base deformities." (PMID 40491596, 2025). "Tumor-induced osteomalacia is characterized by hypophosphatemia and fragility fractures caused by fibroblast growth factor 23 (FGF23)-producing tumors." (PMID 39866919, 2025). "In conclusion, burosumab is a monoclonal antibody against FGF23, which is able to suppress FGF23 expression and reduce the risk of developing FGF23-mediated hypophosphatemia and its associated complications." (PMID 40297189, 2025).
hypophosphatemia (continued). "FGF23 testing is an essential diagnostic tool for determining the cause of hypophosphatemia, with high sensitivity and specificity." (PMID 39866529, 2025). "To date, ferric carboxymaltose, ferric polymaltose, and saccharated ferric oxide have been reported to cause FGF23-related hypophosphatemia, whereas iron dextran, ferumoxytol, and ferric derisomaltose seldom cause this condition." (PMID 39963340, 2025). "Intravenous iron, especially FCM, is an important cause for FGF-23-mediated hypophosphatemia and remained the likely diagnosis in our case." (PMID 41362568, 2025). "FGF23 inhibits renal reabsorption of P in the proximal tubule, causing phosphaturia and subsequent hypophosphatemia." (PMID 40636514, 2025). "FCM leads to a 3–sixfold increase in FGF-23, which in turn leads to an increase in urinary phosphate excretion, thus potentially causing acute hypophosphatemia." (PMID 41146174, 2025). "X-linked hypophosphatemia (XLH) is a genetic disorder characterized by elevated FGF23 levels, leading to phosphate wasting and hypophosphatemia, causing skeletal and extraskeletal abnormalities." (PMID 40323576, 2025). "Among them, situations that stimulate FGF23 transcription, such as iron deficiency anemia and systemic inflammation, induce inappropriately high levels of intact FGF23 and subsequent hypophosphatemia." (PMID 39963340, 2025). "Tumor-induced osteomalacia (TIO), also known as oncogenic osteomalacia, is a rare paraneoplastic syndrome caused by tumors secreting fibroblast growth factor-23 (FGF23), a hormone inducing renal phosphate wasting and subsequent hypophosphatemia." (PMID 39888445, 2025). "This is likely due to a stacking effect of FGF23 and is a well-documented risk factor for post-iron infusion hypophosphatemia." (PMID 41445551, 2025). "In these diseases, altered FGF23 in osteocytes decreases serum phosphate and causes hypophosphatemia." (PMID 40661139, 2025). "FGF23, which is overproduced by PMTs, causes hypophosphatemia and osteomalacia, ultimately leading to multiple insufficiency fractures, which are the cause of TIO symptoms." (PMID 41227266, 2025). "The main cause of XLH is the excessive expression of FGF23, which leads to a reduction in the reabsorption of phosphate in the kidneys and subsequently causes hypophosphatemia." (PMID 40661139, 2025). "Excessive FGF23 production from Gαs-variant bearing osteoprogenitor cells results in renal phosphate wasting in most patients, and frank hypophosphatemia in a subset of patients with high skeletal FD burden." (PMID 41480037, 2025). "published the first case report of iron polymaltose-induced hypophosphatemia associated with FGF23 elevation, and prospectively demonstrated that i.v. iron polymaltose lead to a significant rise in intact FGF23 levels." (PMID 41445551, 2025). "In contrast, one study tested the association of FGF23 and pubertal period in patients with hypophosphatemia and in healthy children." (PMID 40649786, 2025). "As FGF23 is known to cause hypophosphatemia through the downregulation of NPT2a and NPT2c in the proximal renal tubules, the marked hypophosphatemia in this child was likely caused by RAS activation." (PMID 40611284, 2025). "Mutations in the PHEX gene are associated withincreased secretion of FGF-23 by osteocytes, inducing phosphate wasting, hypophosphatemia,impaired endochondral ossification, and alterations of bone matrix and mineralization thatpersist for life." (PMID 40215218, 2025). "Iron infusion with certain formulations, such as ferric carboxymaltose, causes FGF23-mediated hypophosphatemia by reducing FGF23 cleavage to a greater extent than reducing FGF23 transcription." (PMID 41445556, 2025). "OGD patients harboring the p.(Asn330Ile)/N330I variant have FGF23-mediated hypophosphatemia, but the precise mechanism causing hypophosphatemia and FGF23-excess is not fully understood." (PMID 41473314, 2025).
hypophosphatemia (continued). "Tumor-induced osteomalacia (TIO) is a rare paraneoplastic syndrome in which dysregulated secretion of fibroblast growth factor 23 (FGF23) from a tumor causes hypophosphatemia primarily due to renal phosphate wasting." (PMID 39755803, 2025). "Major and well-known causes of acquired FGF23-related hypophosphatemia include TIO and the administration of some intravenous iron preparations." (PMID 39963340, 2025). "An increase in circulating active FGF23 levels causes hypophosphatemia with significantly low or standard levels of 1,25(OH)2D3 and low PTH levels." (PMID 39482539, 2024). "Iron infusion acutely impairs FGF23 cleavage, triggering transient increase in intact FGF23 and hypophosphatemia in association with an inappropriately low concentration of 1,25(OH)2D, similar to genetic diseases of primary FGF23 excess." (PMID 38706696, 2024). "This raises the questionwhether persistent hypophosphatemia after FCM was caused by “inappropriately normal FGF23” orby “inappropriately normal PTH”?" (PMID 38746050, 2024). "Congenital fibroblast growth factor 23 (FGF23)‐related hypophosphatemic rickets/osteomalacia is a rare bone metabolism disorder characterized by hypophosphatemia and caused by genetic abnormalities that result in excessive secretion of FGF23." (PMID 38050660, 2024). "Excessive FGF23 levels result in hypophosphatemia which causes bone abnormalities by inhibiting mineralization and inducing apoptosis of hypertrophic chondrocytes." (PMID 38902808, 2024). "In patients with XLH, FGF23 excess was associated with low or inappropriately normal serum 1,25(OH)2D concentration for the degree of hypophosphatemia." (PMID 37991698, 2024). "Hypophosphatemia associated with normal or low FGF23 concentrations suggests the diagnosis of a form of Fanconi syndrome or HHRH." (PMID 38706696, 2024). "X-linked hypophosphatemic rickets (XLH) is associated with uninhibited FGF23 activity, which leads to phosphaturia, hypophosphatemia and depressed active vitamin D (1,25OH2D) levels." (PMID 39687707, 2024). "The most common adverse effect of iron carboxymaltose is hypophosphatemia, which is caused by an increase in urinary phosphate excretion from the upregulation of the phosphaturic hormone fibroblast growth factor 23 (FGF23)." (PMID 38284706, 2024). "In the present study, we showed for the first time that Bbx deficiency causes hypophosphatemia through the upregulation of FGF23." (PMID 39482539, 2024). "Elevated FGF23 levels cause phosphaturia and hypophosphatemia by the direct suppression of NaPi-2a and NaPi-2c cotransporters in proximal tubular cells, or by affecting parathyroid hormone (PTH) activity." (PMID 39687707, 2024). "Fibroblast growth factor 23 (FGF23) plays an important role in phosphate homeostasis, and increased FGF23 levels result in hypophosphatemia; however, the molecular mechanism underlying increased FGF23 expression has not been fully elucidated." (PMID 39482539, 2024). "The study concluded that fibroblast growth factor 23 plays a major part in FCM-induced hypophosphatemia, most likely by causing phosphate loss through urine." (PMID 39835061, 2024). "The 6H-syndrome is an acronym for hypophosphatemia caused by high FGF23 leadingto hyperphosphaturia and hypocalcitriolemia, which results in hypocalcemia and compensatorysecondary hyperparathyroidism." (PMID 38746050, 2024). "Although the precise mechanism remains to be determined, loss-of-function PHEX mutations result in fibroblast growth factor 23 (FGF23)-induced hypophosphatemia via inappropriately high expression levels of FGF23 in serum." (PMID 39498416, 2024). "Key aspects of the diagnostic process include the assessment of epidermal and/or melanocytic nevi, skeletal dysplasia, fractures, limb deformities, and hypophosphatemia caused by elevated levels of FGF23." (PMID 39416269, 2024).
hypophosphatemia (continued). "FGF23 causes hypophosphatemia and osteomalacia by reducing phosphate reabsorption in proximal tubules and inhibiting 25-hydroxyvitamin D reabsorption by inhibiting 1α-hydroxylation." (PMID 39314547, 2024). "Congenital FGF23‐related hypophosphatemic rickets/osteomalacia is a rare bone metabolism disorder characterized by hypophosphatemia due to excessive secretion of FGF23 caused by genetic abnormalities." (PMID 38050660, 2024). "These tumors produce fibroblast growth factor-23, which causes hypophosphatemia due to renal wasting of phosphate and inhibits vitamin D3 activation, resulting in osteomalacia." (PMID 38389570, 2024). "It is characterized by a mutation of the PHEX gene which results in excess FGF23 production, with abnormal renal and intestinal phosphorus metabolism, hypophosphatemia and osteomalacia secondary to chronic renal excretion of phosphate." (PMID 38117452, 2024). "Tumor-induced osteomalacia (TIO) is a rare paraneoplastic syndrome characterized by hypophosphatemia caused by excessive secretion of fibroblast growth factor-23 (FGF-23) by tumors." (PMID 39749027, 2024). "The loss of FGF23 can generate serious drawbacks such as hypophosphatemia and soft tissue calcifications." (PMID 38732094, 2024). "Increased FGF23 is present in rare diseases inducing enthesopathy, such as XLH and ARHR, findings that implicate a potential causative role for FGF23 or the resultant hypophosphatemia in its pathogenesis." (PMID 37871131, 2024). "In this condition, increased production of fibroblast growth factor-23 leads to renal phosphate wasting, presenting similarly to hypophosphatemia associated with TGS." (PMID 37303415, 2023). "The increase in FGF23 levels, and increased FGF23 signaling in the kidney causing increased Pi excretion, are responsible for hypophosphatemia in hereditary hypophosphatemic disorders." (PMID 37943605, 2023). "It is well known that PHEX mutations induced the over-expression of FGF23, leading to severe hypophosphatemia, also known, specifically, as X-linked hypophosphatemia." (PMID 37374382, 2023). "The prolonged hypophosphatemia was attributed to underlying ADPKD because these patients demonstrate inappropriately elevated FGF23 levels for the degree of severity of reduced glomerular filtration rate." (PMID 37908221, 2023). "In hereditary rickets, FGF23 is produced in excess by bone, resulting in increased serum FGF23 levels that increase renal Pi excretion and cause hypophosphatemia." (PMID 37943605, 2023). "These inactivating mutations of PHEX cause an increased concentration of FGF23, leading to hyperphosphaturia, hypophosphatemia and low or inappropriately normal serum 1,25(OH)2D concentrations." (PMID 37047636, 2023). "HRAS p.G12V expression in dysplastic skeletal lesions increased circulating FGF23, causing hypophosphatemia and osteomalacia." (PMID 36943390, 2023). "Taken together, these data demonstrate that mosaic-like bone expression of HRASG12V causes FGF23-mediated hypophosphatemia and systemic osteomalacia." (PMID 36943390, 2023). "X-linked hypophosphatemia (XLH) is a rare disease of elevated fibroblast growth factor 23 (FGF23) production that leads to hypophosphatemia and poor mineralization of bone and teeth." (PMID 37090634, 2023). "Conditions associated with an FGF23 excess are characterized by hypophosphatemia with excessive phosphaturia for the serum phosphate level and reduced tubular reabsorption of phosphates (TRP)." (PMID 37048797, 2023). "In aggregate, our study suggests that in addition to hypophosphatemia, FGF23 excess and DMP1 deficiency directly control osteoblast differentiation and mineralization in ARHR pathogenesis." (PMID 37943605, 2023). "X-linked hypophosphatemia (XLH: OMIM #307,800) is a genetic disease caused by inactivating mutations in the phosphate regulating endopeptidase homolog, X-linked (PHEX) gene, inducing a fibroblast growth factor-23 (FGF23) mediated hypophosphatemia." (PMID 37530996, 2023).
hypophosphatemia (continued). "The reason for transient hypophosphatemia after intravenous iron substitution therapy is renal phosphate loss caused by iron-induced FGF23 stabilization, secondary hyperparathyroidism, and 25(OH)D resistance." (PMID 37375595, 2023). "The first link between iron deficiency and FGF23 was found in patients with autosomal dominant hypophosphatemic rickets, where FGF23 mutations that impair cleavage occur, resulting in hypophosphatemia." (PMID 36831276, 2023). "Hypophosphatemia due to renal phosphate loss in a setting of normal or low PTH is an accepted indication for FGF23 measurement." (PMID 35665817, 2023). "FGF23 causes hypophosphatemia by inhibiting phosphate reabsorption in proximal tubules of the kidney and phosphate absorption in intestine." (PMID 36686800, 2022). "There are various causes of osteomalacia, such as hypophosphatemia due to excess production of fibroblast growth factor 23, vitamin D deficiency, insufficient vitamin D action, and renal tubular disorders." (PMID 35029240, 2022). "In humans, osteoglophonic dysplasia caused by activating variants in FGFR1 is often associated with hypophosphatemia due to elevated FGF23 levels." (PMID 35909535, 2022). "Hypophosphatemia caused by FGF23 elevation is the main pathophysiological mechanism of FGF23 and XLH." (PMID 35654784, 2022). "Increased levels of FGF23 lead to renal phosphate loss, decreased serum 1,25-dihydroxyvitamin D, and increased metabolism of 1,25-dihydoxyvitamin D, resulting in hypophosphatemia." (PMID 36553684, 2022). "Phosphaturic mesenchymal tumor (PMT) is a rare tumor that secretes fibroblast growth factor 23 (FGF23) and causes hypophosphatemia and tumor-induced osteomalacia (TIO)." (PMID 36686800, 2022). "In XLH, the loss-of-function mutations of the PHEX gene dramatically increase FGF23 production in bone, and the resultant hypophosphatemia causes a decrease in bone mineralization." (PMID 35101067, 2022). "In contrast to iron deficiency, which typically only elevates C-terminal FGF-23, some iron preparations have been commonly associated with hypophosphatemia via an increase in iFGF-23." (PMID 36246903, 2022). "Of these, DMP1 and PHEX are osteogenic marker genes, whose mutations result in hypophosphatemia, low bone mineral density, and elevated FGF23 production." (PMID 35392115, 2022). "Ossicular deterioration in CHL has been demonstrated in other mouse models of FGF23-mediated hypophosphatemia, such as those caused by involvement of Dmp1, a regulator of phosphate homeostasis and mineralization." (PMID 35854274, 2022). "The elevated circulating intact FGF23 levels in aged Hyp mice were associated with hypophosphatemia." (PMID 35884995, 2022). "This article will revise the novel treatment of two conditions that lead to hypophosphatemia with high FGF-23 levels: tumor-induced osteomalacia (TIO) and X-linked hypophosphatemic rickets (XLH)." (PMID 36382755, 2022). "Burosumab treats x-linked patients with hypophosphatemia (XLH) by antagonizing FGF23, increasing renal tubular phosphate reabsorption and normalizing serum phosphorus concentrations." (PMID 36209090, 2022). "FGF23 can be extremely useful during the diagnostic approach since acquired dependent hypophosphatemia (FGF23 ≥ 30 RU/mL) highly suggests TIO." (PMID 35145798, 2022). "An estimated 500 cases of TIO with typical small tumor producing FGF23 and causing hypophosphatemia in adults have been reported." (PMID 35693311, 2022). "In vivo, DMP1 deficiency is associated with enhanced Fgf23 expression with hypophosphatemia, and in vitro DMP1 downregulates FGF23 through NFAT signaling." (PMID 35084563, 2022). "In animal studies, a low-iron diet caused hypophosphatemia in ADHR model mice carrying FGF23[p.R179Q] mutation, along with increased serum levels of both intact FGF23 and C-terminal fragments." (PMID 36246908, 2022).